NALF1 (NALCN channel auxiliary factor 1)
Description:
Auxilary subunit component of the NALCN channelosome complex, which regulates the resting membrane potential by depolarizing sodium leak currents. The NALCN channelosome complex is a voltage-gated ion channel responsible for the resting Na(+) permeability that controls neuronal excitability. The NALCN channelosome is constitutively active and conducts monovalent cations but is blocked by physiological concentrations of extracellular divalent cations.
Synonyms: FAM155A; NLF-1; NLF1
Tractability: Small molecule: a structure with a bound ligand is known. Antibody: UniProt places it where antibodies can reach, with high confidence; its Gene Ontology location is reachable by antibodies, with high confidence; UniProt predicts a signal peptide or a membrane-spanning region.
Gene: Protein-coding gene on chromosome 13 (107,163,510 to 107,867,496, reverse strand). Ensembl gene ENSG00000204442.
Subcellular location: Cell membrane
Gene Ontology:
Molecular function: stretch-activated, monoatomic cation-selective, calcium channel activity
Biological process: regulation of neuronal action potential; sodium ion transmembrane transport; calcium ion import across plasma membrane
Cellular component: plasma membrane; voltage-gated sodium channel complex
Genetic constraint (gnomAD): Loss-of-function variants: 3 observed, 39.33 expected, observed/expected ratio (o/e) 0.0763, 90% interval 0.034 to 0.2. The upper end of that interval is the gene's LOEUF score, 0.2, which puts it in group 1 of 6, group 1 being the genes least tolerant of losing a copy. Missense variants: 486 observed, 523.24 expected, observed/expected ratio (o/e) 0.93, 90% interval 0.86 to 1. Synonymous variants: 243 observed, 229.44 expected, observed/expected ratio (o/e) 1.06, 90% interval 0.95 to 1.18.
Homologues: Orthologues: chimpanzee NALF1 (99% identical), macaque NALF1 (99% identical), rat Nalf1 (89% identical), mouse Nalf1 (89% identical), pig NALF1 (88% identical), dog NALF1 (88% identical), tropical clawed frog nalf1 (61% identical), rabbit NALF1 (59% identical), guinea pig NALF1 (52% identical), zebrafish nalf1a (48% identical), Drosophila melanogaster Mid1 (24% identical). Paralogues in human: NALF2 (42% identical).
Diseases named in the same sentence as NALF1 in open-access papers:
NALF1 is named in the same sentence as 11 diseases in open-access papers, as found by Europe PMC text mining. Sharing a sentence is not in itself a finding about the gene and the disease.
NALF1 shares sentences with these, for which no sentence is quoted: diverticulitis (2 papers); breast carcinoma (1); cancer (1); developmental delay (1); diverticular disease (1); gastric cancer (1); HIV-1 infection (1); Intellectual disability (1); Obesity (1); renal clear cell carcinoma (1); tumor (1).